CHAT (choline O-acetyltransferase)
Description:
Catalyzes the reversible synthesis of acetylcholine (ACh) from acetyl CoA and choline at cholinergic synapses.
Synonyms: CHOACTase; CMS1A; CMS1A2; CMS6
Tractability: Small molecule: a structure with a bound ligand is known; it has a binding pocket of medium quality; it belongs to a druggable protein family. PROTAC: a small molecule that binds it is known.
Target class: Enzyme; Transferase
Gene: Protein-coding gene on chromosome 10 (49,609,095 to 49,667,942, forward strand). Ensembl gene ENSG00000070748.
Pathways (Reactome):
Metabolism: Synthesis of PC
Neuronal System: Acetylcholine Neurotransmitter Release Cycle
Gene Ontology:
Molecular function: choline O-acetyltransferase activity; acyltransferase activity
Biological process: acetylcholine biosynthetic process; neuromuscular synaptic transmission; neurotransmitter transport; phosphatidylcholine biosynthetic process
Cellular component: cytoplasm; cytosol; neuron projection; nucleus; synapse
Genetic constraint (gnomAD): Loss-of-function variants: 61 observed, 77.62 expected, observed/expected ratio (o/e) 0.79, 90% interval 0.64 to 0.97. The upper end of that interval is the gene's LOEUF score, 0.97, which puts it in group 4 of 6, group 1 being the genes least tolerant of losing a copy. Missense variants: 933 observed, 990.96 expected, observed/expected ratio (o/e) 0.94, 90% interval 0.89 to 0.99. Synonymous variants: 399 observed, 397.38 expected, observed/expected ratio (o/e) 1, 90% interval 0.92 to 1.09.
Homologues: Orthologues: chimpanzee CHAT (99% identical), macaque CHAT (94% identical), dog CHAT (78% identical), pig CHAT (77% identical), rat Chat (76% identical), mouse Chat (75% identical), rabbit CHAT (74% identical), guinea pig CHAT (71% identical), tropical clawed frog chat (60% identical), zebrafish chata (55% identical), Drosophila melanogaster ChAT (35% identical), Caenorhabditis elegans cha-1 (28% identical). Paralogues in human: CRAT (35% identical), CPT1A (27% identical), CPT1B (25% identical), CPT1C (25% identical), CROT (24% identical), CPT2 (24% identical).
Diseases named in the same sentence as CHAT in open-access papers:
CHAT is named in the same sentence as 165 diseases in open-access papers, as found by Europe PMC text mining. Sharing a sentence is not in itself a finding about the gene and the disease. The quoted sentences say what the papers report.
Cognitive impairment (65 papers, 2009 to 2026). Abnormal cognition is characterized by deficits in thinking, reasoning, or remembering. "AIE deficits in reversal learning are linked to the ChAt loss by anti-inflammatory indomethacin, exercise, and galantamine treatments during AIE that prevent the loss of ChAT+ neurons and cognitive deficits." (PMID 38524847, 2024). "We previously reported that exercise during or following AIE treatment can restore ChAT +, TrkA +, and p75NTR + loss as well as associated adult cognitive deficits." (PMID 33716687, 2021). "Although loss of cholinergic neurons was initially thought to involve ChAT + neuron loss and cognitive deficits, our exercise reversal studies support a reversal of epigenetic programming." (PMID 33716687, 2021). "Dysfunction of presynaptic cholinergic system marked by decreased choline acetyltransferase (ChAT) activity causes cognitive deficits." (PMID 30410227, 2018). "A human and primate specific 82-kDa variant of choline acetyltransferase (82-kDa ChAT) was also found to have altered localization in cholinergic neurons of patients diagnosed with mild cognitive impairment (MCI) and AD." (PMID 29541020, 2018). "The cognitive impairment is mainly due to loss of neurotransmitter ACh caused by reduced activity of choline acetyltransferase (ChAT), an enzyme evolved in synthesis of ACh." (PMID 29078760, 2017). "The presence of visual hallucinations and global cognitive impairment are also associated with deficits in choline acetyltransferase (ChAT) in DLB." (PMID 23398715, 2013). "As a cluster of clues indicates that cholinergic system alterations underlie age-related cognitive impairments, it was crucial to know how age impacts ChAT-Cre mice, and whether these changes can occur as early as at middle-age." (PMID 35925937, 2022). "Treatment with naringenin increases ChAT in the hippocampus in a rat model of Alzheimer’s disease- (AD-) type neurodegeneration with cognitive impairment (ADTNDCI), with a concomitant decrease in the loss of ChAT positive neurons and impairments in spatial learning and memory." (PMID 29083387, 2015). "Therefore, the estradiol deficiency induced memory loss by the down-regulation of the neurotrophin family and F3.ChAT could ameliorate the cognitive impairment owing to the loss or reduction of estradiol." (PMID 35628371, 2022). "Next, we injected an adeno-associated virus with ChAT-driven chemogenetics to inhibit the basal forebrain-hippocampus circuit, clarifying whether EA treatment could promote hippocampal neurogenesis to improve cognitive impairments via this neural circuit." (PMID 35185516, 2021). "A study showed that in the prefrontal cortex of 44 patients with AD, reduced choline acetyltransferase (ChAT) activity was related to cognitive impairment, which synthesized the neurotransmitter ACh." (PMID 38379403, 2025). "In cases of cognitive impairment, decreased levels of Ach, AchE and increased levels of protein carbonyl and ChAT have been observed." (PMID 38055394, 2023). "We further clarified THPH’spossible mechanism of improving cognitive impairment and memory by studying the expression of AchE and ChAT genes in the brain." (PMID 34945680, 2021). "Studies have shown that CCH decrease ChAT activities and ACh levels in rats' brains, and that it is closely related to cognitive impairment in rats." (PMID 34136148, 2021). "SA attenuated the cognitive impairment by restoring the acetylcholine levels through up-regulation of ChAT protein expression." (PMID 33266113, 2020). "It has been reported that levels of ChAT decrease in Alzheimer’s patients with severe cognitive impairment and the same has been observed in ICV-STZ-induced cognitive impairment." (PMID 33266113, 2020). "In line with the ChAT reduction in L1, hippocampal AChE levels have been reported to be significantly reduced in patients with mild cognitive impairment and early Alzheimer’s disease, displaying robust correlations to cognitive impairment." (PMID 32954291, 2020).
Cognitive impairment (continued). "The reduced levels of ChAT reflect deficits in acetylcholine homeostasis that contribute to cognitive impairment with neurodegeneration." (PMID 20302640, 2010). "For example, there are several manuscripts targeting cholinergic pathway as a protective mechanism against cognitive impairment, the increase in ChAT+ cells could improve cognitive deficits and modulate neuroinflammation." (PMID 41230091, 2025). "Changes in ChAT activity suggest that chronic social defeat stress may disrupt cholinergic signaling, potentially contributing to cognitive deficits and emotional dysregulation observed in chronic social defeat stress models." (PMID 40649841, 2025). "The ability of hNGFp to rescue ChAT expression is thus of the utmost importance, as it might have beneficial effects on the cognitive impairment of patients with Rett syndrome." (PMID 37633263, 2024). "Additionally, 476 proved to increase the expression of pAkt and pERK, and ChAT-positive area in the hippocampal regions of surgery-treated mice proved to effectively attenuate scopolamine-induced cognitive impairments in vivo and be less toxic than THA." (PMID 36675233, 2023). "In addition, in the ICV-STZ-induced cognitive impairment model, ACh levels were restored through the upregulation of ChAT protein expression to alleviate cognitive impairment." (PMID 36979237, 2023). "The result suggests the sevoflurane improved the cognitive impairment after the isoflurane treatment may be involved in the activity of Ach, ChAT and AchE." (PMID 38055394, 2023). "In addition, cornuside isolated from C. fructus ameliorated cognitive impairment by increasing ACh level and ChAT activity and decreasing AChE activity in scopolamine-induced AD mice." (PMID 36613533, 2022). "However, less is known regarding the levels of the ACh-synthesizing enzyme ChAT and the ACh-degrading enzyme AChE in CSF and plasma in patients with cognitive impairment." (PMID 34512307, 2021). "SA normalized the ChAT expression and mitigated the cognitive impairment in rats." (PMID 33266113, 2020). "In addition, SCO treatment significantly decreased Ach levels and expression of ChAT protein while increasing AChE activity in both the hippocampus and cortex, suggesting that the observed cognitive impairments were induced by cholinergic dysfunction." (PMID 31141948, 2019). "The protein express and activity of ChAT decreased at early stages of AD and cognitive impairment." (PMID 30050927, 2018). "The cholinergic system is essential for adaptive learning and memory, and thus the ECS-related cognitive deficits observed in this study may well be related to the co-occurring changes in ChAT-based cholinergic fiber density." (PMID 28910337, 2017). "Stilbene glucoside, another major extract of Radix Polygoni Multiflori, could improve the cognitive impairment by reducing oxidative stress and increasing the activity of choline acetyl transferase (ChAT)." (PMID 28018474, 2016). "Since scopolamine has been used in the standard cognitive impairment model, there were a lot of literatures to show that the effects of scopolamine treatment can induce cognitive deficit through decreasing ACh contents and ChAT activities while increasing AChE activities in the hippocampus." (PMID 34073796, 2021). "Degeneration of BFCNs and ChAT + somal shrinkage is a feature of several neurodegenerative disorders, including AD and AUD, and may contribute to the cognitive deficits associated with these disorders." (PMID 33716687, 2021). "Based on an ubiquitous expression of ChAT, one might speculate that cognitive impairment observed in some patients might result from tissue-specific functions of the proteins which can (in some cases) only partially be compensated upon loss of the functional protein." (PMID 33364925, 2020).
Cognitive impairment (continued). "In current study, we find that SCOP decreases ACh content and ChAT activity, increases activity of AChE in both hippocampus and cortex, which indicate that the dysfunction of cholinergic nervous system might facilitate the process of cognitive impairment." (PMID 28852153, 2017). "Furthermore, exogenous administration of ChAT attenuates cognitive impairments in aged mice." (PMID 25705233, 2015). "Thus, modulation of the cholinergic signaling pathway, such as inhibition of AChE, activation of ChAT, and promotion of ACh synthesis, may serve as strategies for the treatment of memory dysfunction due to AD or poststroke cognitive impairments." (PMID 24194776, 2013). "While T2DM subjects showed comparable ChAT-ir to controls, epidemiological studies link T2DM with cognitive impairments." (PMID 41023469, 2025). "Cortical hypofunction was also found after ChAT-specific Cul3 ablation and stimulation of cholinergic projections from the BF to the prefrontal cortex (PFC) mitigated cognitive deficits." (PMID 36693858, 2023). "The present study analyzed the effect of 10% hexane solvent on Bean-PS-attenuated TMT-induced cognitive defects in the Morris water maze, and found a protective effect in contrast to TMT-induced reduction in ChAT and AchE in the hippocampal areas." (PMID 32664537, 2020). "The arising question is to know whether ChAT-IRES-Cre mice, that have moderate cholinergic system alteration, show earlier evolution of age-related cognitive impairments." (PMID 35925937, 2022). "Indeed, degeneration of BFCNs and ChAT + somal shrinkage are features of several neurodegenerative disorders, including AD and AUD, and may contribute to the cognitive deficits associated with these disorders, all of which are also associated with increased expression of neuroimmune genes." (PMID 33716687, 2021). "However, there is still a lack of knowledge on the levels of the key cholinergic enzymes ChAT and AChE in CSF and plasma in untreated patients with AD and in individuals with mild cognitive impairment (MCI) or subjective cognitive impairment (SCI)." (PMID 34512307, 2021). "When clozapine N-oxide (CNO, 1 mg/kg) was intraperitoneally administered to activate BF cholinergic neurons, behavioral abnormalities were completely ameliorated in the ChAT-Cre;Hrh1fl/fl mice, including disrupted PPI, social impairments, anhedonia-like behavior, and cognitive impairments." (PMID 33602941, 2021). "Thus, the expression of AchE and ChAT in the hippocampus and its relation to TMT-induced cognitive impairment in rats was examined." (PMID 32664537, 2020). "ECS increased microglial activity and decreased ChAT activity in the hippocampus of CSS and control mice, thus supporting a role for cholinergic alterations and neuroimmune activation in ECT/ECS-induced cognitive deficits." (PMID 28910337, 2017). "This is consistent with previous reports of Aβ oligomers inducing a major reduction in ChAT activity and the lack of ChAT viability by attaching specifically to excitatory synapses, leading to cholinergic synapse dysfunction and cognitive impairment." (PMID 28671572, 2017). "The fact that ChAT expression and cognitive function were most impaired in the NDEA+HFD group relative to control vis-à-vis low levels of AβPP-Aβ highlights the controversial role of AβPP-Aβ accumulation in relation to cognitive impairment in AD." (PMID 20034403, 2009). "Based on the scopolamine-induced cognitive impairment, we studied the behavioral phenotype of AD model mice and discovered that GPCRAC extracts at high doses markedly alleviate AD-related cholinergic dysfunction, as demonstrated by increased Ach content and ChAT activity and decreased AchE activity." (PMID 35295332, 2022).
Cognitive impairment (continued). "One striking example is that ChAT–ChR2–EYFP mice carry extra copies of the vesicular acetylcholine transporter gene, which leads to overexpression of the gene VAChT, consequent increased cholinergic tone, and behavioral changes with improved motor endurance and severe cognitive deficits." (PMID 28562670, 2017). "A significant decrease in ChAT-positive varicosities was found in PD-MCI (p = 0.0275) and PDD (p = 0.0207) cases compared with PD cases with no cognitive impairment." (PMID 31023342, 2019).
Alzheimer disease (41 papers, 2008 to 2024). A progressive, neurodegenerative disease characterized by loss of function and death of nerve cells in several areas of the brain leading to loss of cognitive function such as memory and language. "Cognitive dysfunction in Alzheimer’s disease (AD) patients correlates significantly with reduced choline acetyl transferase (ChAT) activity and the loss of cholinergic neurons." (PMID 39598829, 2024). "By enhancing ChAT activity and antioxidant effects, sECC obviously countered cognitive decline associated with Alzheimer’s disease." (PMID 39598829, 2024). "Alzheimer’s disease has been previously associated with cholinergic neuron loss in the basal forebrain and deficits in choline O-acetyltransferase (encoded by CHAT)." (PMID 34194426, 2021). "The most common CMS-EA gene, CHAT, has important functions in both central and peripheral synapses, and deficiency of ChAT has been reported in Alzheimer’s disease, idiopathic Parkinson’s disease, Huntington’s disease and schizophrenia." (PMID 29189923, 2018). "Firstly, this study is the first meta-analysis to investigate the association of CHAT rs2177369 polymorphism with the development of Alzheimer's disease." (PMID 27597977, 2016). "We further report differential CSF levels of ChAT in relation to Alzheimer’s disease risk genotypes, as well as in patients with multiple sclerosis, a chronic neuroinflammatory disease, compared to controls." (PMID 23840379, 2013). "Therefore, degenerative changes in cholinergic nerves in aged persons and Alzheimer’s disease (AD) patients result in learning and memory loss following the disintegration of the cholinergic factors, including ChAT." (PMID 38067139, 2023). "Indeed, ChAT deficiency has been reported in various developmental and neurodegenerative disorders, including Alzheimer’s disease, Huntington’s disease, amyotrophic lateral sclerosis, Schizophrenia, Rett syndrome, and Sudden Infant Death Syndrome (SIDS)." (PMID 30914958, 2019). "A decreased activity of choline acetyltransferase (ChAT) and the subsequent altered ACh synthesis are correlated with an increased formation of ß-amyloid (Aβ) plaques in the brains of patients with Alzheimer’s disease (AD)." (PMID 37513246, 2023). "The immunoreactivity of ChAT is often used as a marker of cognitive decline in various neurodegenerative diseases such as Alzheimer’s disease (AD)." (PMID 33298129, 2020). "Neuropathological evidence indicates decreases of cholinergic interneurons with reduced choline acetyltransferase (ChAT) activities in the striatum of patients with Alzheimer’s disease." (PMID 31001802, 2019). "In Alzheimer’s disease, amyloid-beta (Aβ) peptides promote damage of presynaptic cholinergic system and decrease in choline acetyltransferase (ChAT) activity." (PMID 31075951, 2019). "As the enzyme responsible for the biosynthesis of acetylcholine, CHAT protein is a marker of evaluating the function of basal forebrain cholinergic cells, the dementia severity in Alzheimer's disease and the density of senile plaques." (PMID 24039871, 2013). "ChAT nuclear downregulation or export is thought to be involved detrimentally in human aging and Alzheimer’s disease, where the magnocellular cholinergic neuron dysfunction in the basal forebrain is at risk of causing age- and disease-related memory and cognitive decline." (PMID 39201793, 2024). "Garsubellin A with a cyclohexanone skeleton is a potent inducer of choline acetyltransferase (ChAT) and could be used for the treatment of Alzheimer's disease." (PMID 39161707, 2024). "Additionally, it has been asserted that overexpressing ChAT in a rat model of Alzheimer’s disease can enhance cognitive functions by raising acetylcholine levels." (PMID 36385687, 2023). "Actually, we developed F3.ChAT human NSCs for the therapy of human Alzheimer’s disease (AD)." (PMID 38067139, 2023).